HMGB1 (high mobility group box 1)
Diseases named in the same sentence as HMGB1 in open-access papers (continued):
Sharing a sentence is not in itself a finding about the gene and the disease.
Sepsis (continued). "CircTLK1 aggravates mtDNA oxidative damage, mitochondrial dysfunction and cardiomyocyte apoptosis by activating HMGB1 during sepsis." (PMID 35720285, 2022). "angelica sinensis has protective effect against lethal endotoxemia and experimental sepsis, in part by reducing systemic accumulation of the late pro-inflammatory cytokine HMGB1." (PMID 35720285, 2022). "Previous reports have shown that the M2 isoform of pyruvate kinase muscle 2 (PKM2) regulates glycolysis to promote IL-1β and HMGB1 release in LPS-stimulated macrophages during sepsis pathogenesis." (PMID 34697412, 2022). "ELISA showed that the HMGB1 and IL-10 levels were higher in patients with sepsis than in healthy donors." (PMID 35983056, 2022). "Down-regulation of lncRNA PVT1 by miRNA-29a/HMGB1 axis attenuates the polarization of macrophage M1 and alleviates sepsis-induced myocardial injury." (PMID 35720285, 2022). "SB1 and SB2, which are derived from black ginsen, reduces the cecal ligation and puncture-induced release of HMGB1, sepsis-related mortality, and tissue injury in vivo." (PMID 35720285, 2022). "Acute inflammatory and infective processes, such as acute kidney injury and sepsis, determine high HMGB1 levels." (PMID 36498479, 2022). "Elevated levels of PF4+ pEVs have been reported in sepsis, and there is evidence that HMGB1+ pEVs are significantly elevated in COVID-19." (PMID 35874830, 2022). "Release of HMGB1 from activated and/or necrotic tissues plays a pivotal role in triggering the proinflammatory cascade of late sepsis." (PMID 33658363, 2021). "Among the four members of HMGB, HMGB1 is considered as a potential therapeutic target for sepsis, and glycyrrhizin protects rats from sepsis-induced damage by preventing the HMGB1-mediated inflammation." (PMID 34092219, 2021). "The circulating levels of HMGB1 can remain elevated for up to eight weeks in sepsis-surviving mice (>20 ng/mL)." (PMID 34208101, 2021). "Many experiments have shown that Era, an inhibitor of ferroptosis, can relieve sepsis induced by CLP or LPS in mice, which is associated with a reduced level of inflammatory cytokines such as tumor necrosis factor (TNF)-α, IL-1β, and HMGB1." (PMID 34482365, 2021). "Our research reveals that circPTK2 regulates microglia activation and hippocampal neuronal apoptosis induced by sepsis via miR-181c-5p-HMGB1 signaling." (PMID 33952191, 2021). "In conclusion, these results suggest that all biomarkers analyzed show a very similar distribution pattern, with HMGB1 showing the highest levels in sepsis patients as compared to septic shock ones." (PMID 34576097, 2021). "In sepsis, HMGB1 not only triggers neutrophil recruitment but also induces macrophages and endothelial cell stimulation for proinflammatory cytokine production." (PMID 33947887, 2021). "The plasma levels of HMGB1 in patients with septic shock were significantly higher than those in sepsis patients [4.0 ng/mL (2.4–5.8) vs. 5.0 ng/mL (4.0–6.5), P = 0.023]." (PMID 33947887, 2021). "Future studies should explore the translational implication of platelet-derived HMGB1 as novel therapeutic targets in humans and dogs with sepsis." (PMID 34235204, 2021). "Recent reports and reviews have paid much attention to the therapeutic effects of HMGB1 on the inflammatory diseases, not limited to sepsis." (PMID 34906140, 2021). "The alarmin molecule, High Mobility Group Box 1 (HMGB1), is an activator of NF-κB and has been recognized as an important mediator of sepsis and lung injury in preterm infants." (PMID 33407269, 2021). "An HMGB1/PTEN/β-catenin cascade modulates the development and involvement of regulatory T cells in sepsis-associated lung injury." (PMID 33925132, 2021). "The timing of HMGB1 release therefore depends on the extent of kidney failure predominant at the onset of sepsis." (PMID 33732235, 2021).
Sepsis (continued). "DADLE reduced serum levels of HMGB1 and the production of proinflammatory cytokines in a rat model of sepsis induced by cecal ligation and puncture, in which the role of TLR4 was shown." (PMID 34616852, 2021). "In the derivation cohort, the plasma HMGB1 levels of the control (n = 46, 24.5%), sepsis (n = 58, 30.9%), and septic shock (n = 84, 44.7%) groups were significantly increased (P < 0.001)." (PMID 33947887, 2021). "The HMGB1 protein is considered a specific marker of sepsis due to its role in inflammatory progression." (PMID 34575863, 2021). "A previous study had revealed that ITGAM mainly contributed to the progression of sepsis by promoting the nuclear, cytoplasmic translocation and activating release of HMGB1." (PMID 33949285, 2021). "The suppressed expression of CD80, CD86, and MHC-II was reversed by inhibiting cerebral HMGB1 at 48 h after sepsis." (PMID 34512319, 2021). "A previous study has shown that hepatocyte-released high mobility group box 1 (HMGB1) mediates caspase-11–dependent lethality in sepsis by delivering extracellular LPS into the cytosol." (PMID 34093202, 2021). "Many studies have reported that the NLRP3 inflammasome is involved in HMGB1 elevation in sepsis, inflammatory kidney disease, acute lung injury, and other infectious diseases, and most studies have focused on immune cells such as macrophages and microglia." (PMID 34539383, 2021). "Accordingly, we have developed a panel of TN-specific mAbs that effectively prevented both harmful HMGB1/TN interaction and resultant macrophage pyroptosis and lethal sepsis." (PMID 34571869, 2021). "The results showed that the levels of the pro-inflammatory cytokines IL-6 and IL-8 and several chemokines (CXCL-8, keratinocyte-derived chemokine, and CCL2), and high-mobility group box-1 (HMGB-1) were higher in dogs with sepsis than in the healthy controls." (PMID 33718468, 2021). "During sepsis, HMGB1 is secreted into the extracellular milieu after stimulating by bacterial endotoxin or pro-inflammatory cytokines." (PMID 33842398, 2021). "As reported in our previous study, the release of cerebral HMGB1 was confirmed to have critical involvement in the development of sepsis-induced brain injury." (PMID 34512319, 2021). "The role of HMGB1 in sepsis has been extensively explored in rodent models with cecal ligation and puncture (CLP)." (PMID 33925132, 2021). "High mobility group box 1 (HMGB1) is known as a later inflammatory mediator and is critically involved in the severity and prognosis of sepsis by inducing intractable inflammation and dysfunction of various immune cells." (PMID 34512319, 2021). "Studies also demonstrate that even delayed treatment with Box A is capable of specific inhibition of endogenous HMGB1 and therapeutically reversed lethality of established sepsis." (PMID 34684184, 2021). "In the present study, we found that increased level of brain HMGB1 was related to immune dysfunction of splenic DCs in sepsis, as shown by suppressed expression of surface molecules and disturbed priming activity for T cells." (PMID 34512319, 2021). "Much later, HMGB1 was found to be passively or actively released in conditions like sepsis, leading to inflammation, that is, it is a DAMP." (PMID 33658363, 2021). "Among the PAMPs and DAMPs associated with the challenging septic response, citrullinated histone H3 and HMGB1 have been suggested as potential sepsis biomarkers." (PMID 34576097, 2021). "The finding of surface expression of HMGB1 in LPS-activated platelets via TLR4 offers a contribution to the study of translational sepsis research." (PMID 34235204, 2021). "Some other studies revealed that Paeonol reduces sepsis by promoting the miR-339-5p expression to repress the HMGB1 and IKK-β-mediated inflammation." (PMID 34366853, 2021). "HMGB1, a critical inflammatory mediator, was released during sepsis, increasing 3–24 h after LPS treatment." (PMID 34445236, 2021).
Sepsis (continued). "Our results further confirm that severe infection of bacteria in sepsis stimulates inflammatory immune responses through HMGB1/TLR2/MyD88 activation signal pathway as shown for other helminth-derived proteins." (PMID 33842398, 2021). "Substantial evidence indicated the SIRT1-modulated deacetylation of HMGB1 alleviated inflammation, restored renal function, and prolonged the survival time of mice with sepsis-related acute kidney injury." (PMID 34906140, 2021). "GLN was found to elicit a more-balanced T helper cell polarization, decreased programmed cell death 1 expression on immune cells, and downregulated high-mobility group box protein-1- (HMGB-1-) mediated pathway, thus alleviating kidney injury in sepsis." (PMID 33859538, 2021). "Our findings provide evidence that targeting circTLK1/miR‐17‐5p/PARP1/HMGB1 axis confers an effective protection against sepsis‐induced myocardial injury." (PMID 34410682, 2021). "To deduce the function of serum HMGB1+ EVs in sepsis patients, we injected HMGB1-low serum EVs and HMGB1-high serum EVs into wild-type mice." (PMID 34743181, 2021). "Subsequent HMGB1 occurrence in plasma and locally released by the brain acts, for example, as a late mediator of sepsis or contributes to high fat diet-induced hippocampal inflammation i.e., obesity." (PMID 34208101, 2021). "In summary, we explored the role of circPTK2-miR-181c-5p-HMGB1 in hippocampal neuronal apoptosis induced by sepsis via miR-181c-5p-HMGB1 signaling." (PMID 33952191, 2021). "HMGB1 mediates anemia of inflammation by interfering with erythropoiesis in murine sepsis survivals." (PMID 33925132, 2021). "Elevated levels of circulating HMGB1 have been reported in humans with cardiovascular diseases like ischemic stroke, deep vein thrombosis, peripheral arterial disease as well as sepsis and disseminated intravascular coagulation." (PMID 34235204, 2021). "In conclusion, we identified that circTLK1 contributed to sepsis-associated AKI by regulating inflammation and oxidative stress through the miR-106a-5p/HMGB1 axis." (PMID 34250012, 2021). "Our data demonstrated that LPS injection prominently upregulated the levels of lactate and HMGB1 in serum, while AE prominently downregulated the levels of lactate and HMGB1 in serum during sepsis." (PMID 34493741, 2021). "Excessive accumulation of extracellular HMGB1 in tissue or circulation contributes significantly to the pathogenesis of many inflammatory or autoimmune diseases such as sepsis and colitis." (PMID 34066647, 2021). "Extracellular HMGB1 contributes to a variety of inflammatory diseases, such as rheumatoid arthritis, and lethal endotoxaemia and sepsis, which can be ameliorated by HMGB1 inhibitors, such as glycyrrhizin, via blocking HMGB1 release." (PMID 34008469, 2021). "In the present study, we uncovered that circTLK1 contributed to sepsis-associated AKI by regulating inflammation and oxidative stress through the miR-106a-5p/HMGB1 axis." (PMID 34250012, 2021). "We suggest that the potent inflammatory effects of HMGB1 are kept in check via sequestration by plasma sialoglycoproteins at physiological pH and triggered when pH and zinc levels fall in late stages of sepsis." (PMID 33658363, 2021). "Targeting HMGB1 was considered as a potential therapeutic option for the treatment of sepsis owing to the fact that patients who manifested as prolonged inflammatory responses frequently displayed continued high HMGB1 levels." (PMID 34906140, 2021). "Previous data showed the essential involvement of cerebral HMGB1 in sepsis-induced dysfunction of splenic DCs, as evidenced by inhibiting expressions of surface molecules and priming activity for T cells." (PMID 34512319, 2021). "In PINK1–PARK2 gene knockout mice, a decrease in the circulating level of the neurotransmitter dopamine has been observed, as well as activation of NLRP3 inflammasome and overexpression of downstream sepsis mediator, HMGB1." (PMID 34257519, 2021).
Sepsis (continued). "During sepsis, the alarmin HMGB1 secrets from tissues and induces systemic inflammation through interacting with multiple target cell receptors, and then results in multiorgan injury." (PMID 33645622, 2021). "More importantly, this study demonstrated that late administration of anti-HMGB1 antibodies was able to treat mice with clinical signs of shock, which makes this strategy very interesting in the treatment of human sepsis." (PMID 33732235, 2021). "The use of Box A has been extensively accepted as an antagonist of HMGB1 and shown significant protection against multiple organ injury and sepsis lethality." (PMID 34512319, 2021). "It has been documented that serum HMGB1 was significantly increased during sepsis and was responsible for multiple organ dysfunction and lethality in septic patients." (PMID 34512319, 2021). "A novel RAGE-overexpressed vector was synthesized via recombinant DNA technology thereafter, and the ALI mice were treated with DEX or RAGE-overexpressed lentivirus to further investigate the specific regulatory mechanisms of RAGE/HMGB1 in sepsis-related ALI." (PMID 34747306, 2021). "Unlike burn models that are lethal in the absence of infection, this nonlethal burn model allowed us to examine the independent effects of the burn on the host response and identify a critical role for HMGB1 in burn wound sepsis." (PMID 34152806, 2021). "As detailed earlier, HMGB1 has been shown to mediate endotoxin delivery to the cytosolic compartments of macrophage and endothelial cells during sepsis, leading to the activation of caspase-11 and induction of pyroptosis." (PMID 33546173, 2021). "Extracellular HMGB1 is identified as a late inflammatory mediator that drives uncontrolled inflammatory response and is considered a potential therapeutic target for sepsis." (PMID 34512319, 2021). "When SIRT1 is activated in cecum ligation and puncture (CLP) models and LPS-induced cell lines, the expression, translocation, and release of HMGB1, which are the most important factors in sepsis, decreased." (PMID 34445236, 2021). "In the CLP mouse model, the concentration dynamics of AGEs and HMGB1 in the blood differed; AGEs increased in the early stage of sepsis and peaked at 3 h after CLP, while HMGB1 accumulated in the blood over time." (PMID 33436632, 2021). "Many preclinical studies show protection against sepsis upon injection of blocking antibodies of HMGB1 or injection of Box A protein." (PMID 33658363, 2021). "Our previous study found that hepatocyte-released HMGB1 delivers extracellular LPS into the cytosol of macrophages and mediates caspase-11–dependent pyroptosis in sepsis." (PMID 34093202, 2021). "HMGB1 appears much later than other proinflammatory cytokines after onset of sepsis: LPS stimulation of mouse macrophages upregulated HMGB1 within 8 h, followed by a massive increase at 16–32 h." (PMID 33925132, 2021). "HMGB1 has two LPS-binding peptide regions that can be utilized to design anti-sepsis or LPS-neutralizing therapeutics in a mouse model." (PMID 33925132, 2021). "Recently, high-mobility group box 1 (HMGB1) has been identified as the crucial positive contributor to sepsis, and HMGB1 inhibition provides a higher therapeutic window." (PMID 34250012, 2021). "To our knowledge, we have demonstrated, for the first time, the association of plasma levels of surrogate markers of necroptosis activity RIPK3 and MLKL, with that of HMGB1 in patients with sepsis." (PMID 33947887, 2021). "As a late inflammatory mediator, HMGB1 can be induced by LPS and it participates in pyroptosis during the pathogenesis of sepsis via the secretion of pro-inflammatory factors, such as TNF-α, IL-1, II-6, and IL-8." (PMID 33714207, 2021). "AE, which impaired HMGB1 release during sepsis, was a new therapeutic strategy targeting aerobic glycolysis for sepsis." (PMID 34493741, 2021).
Sepsis (continued). "Previous research has shown that HMGB1 appears to be an early stage mediator in trauma, while HMGB1 is conversely a late-stage mediator in sepsis." (PMID 34743181, 2021). "For instance, shikonin-induced PKM2 inhibition in activated macrophages led to a reduction in the release of HMGB1 and protected against LPS-induced endotoxemia and sepsis in mice." (PMID 33503959, 2021). "In contrast, the engagement of RAGE by HMGB1 can adversely impair neutrophil NADPH-dependent production of reactive oxidation species (ROS) and associated bacterial killing, contributing to sepsis-induced immune paralysis and immuno-suppression." (PMID 34571869, 2021). "Apart fromit, oleuropein also led to a significant decline in the levels of HMGB1 in the hearthomogenates suggesting its ameliorative effects on sepsis." (PMID 33605309, 2021). "AE prominently downregulated CXCL-1, CXCL-8, IL-6, TNF-α, Glu1, and HMGB1 mRNA expression but activated IL-1RN, IL-10, Sirt-1, and Nrf-2 mRNA expression in the lung during sepsis." (PMID 34493741, 2021). "Our present results, however, broaden such evidence for incidences where LPS increases plasma levels of HMGB1 that precede the inflammatory response in the brain, like during sepsis or obesity." (PMID 34208101, 2021). "In line with the experimental sepsis studies, HMGB1 would thus be a late mediator of a potentially fatal dysregulated host response in CVID-19." (PMID 33939645, 2021). "While tumor necrosis factor α and interleukin 1β are released early during sepsis, HMGB1 is a late mediator expressed only after about 24 h and remains at elevated levels before death occurs." (PMID 33658363, 2021). "In the current study, activation of the NLRP3 inflammasome accompanied by increased secretion of IL-1β, IL-18, and HMGB1 was noted in CD11c+CD11bintMHC-IIhiCD115−Flt3+ splenic DCs after induction of sepsis." (PMID 34741186, 2021). "During sepsis, secretions of pro-inflammatory HMGB1 by endothelial cells can upregulate the expression of CAMs to promote the inflammatory response by recruiting leukocytes." (PMID 34507301, 2021). "As a multi-functional protein, HMGB1 has been widely investigated and considered an essential facilitator in diseases such as sepsis, collagen disease, atherosclerosis, cancers, arthritis, and acute lung injury and myocardial infarction." (PMID 33128580, 2021). "HMGB1 emerges as a highly conserved protein that was first identified to modulate sepsis in a murine model." (PMID 34906140, 2021). "Additional studies identifying the kinetics of plasma HMGB1 are essential to better understand the role of HMGB1 as a biomarker and its meaning in the pathogenesis of sepsis." (PMID 33947887, 2021). "It has been evidenced that circulating levels of HMGB1 are boosted in patients with sepsis, and septic patients with a higher level of HMGB1 are more susceptible to DIC and organ dysfunction." (PMID 34093202, 2021). "The median levels of HMGB1 for the control, sepsis, and septic shock groups were 2.4 (0.6–4.6) ng/mL, 3.1 (2.0–5.3) ng/mL, and 5.7 (2.6–8.0) ng/mL, respectively." (PMID 33947887, 2021). "HMGB1-mediated cytosolic delivery of LPS is critical for caspase-11 activation in endotoxemia or sepsis." (PMID 33854044, 2021). "The optimal cut-off level of HMGB1 for predicting the 28-day mortality in 142 sepsis patients was 5.9 ng/mL." (PMID 33947887, 2021). "High-mobility group protein 1 (HMGB1) is identified as a DAMP molecule-mediated inflammatory response in sepsis, cancer, and immune diseases." (PMID 34747306, 2021). "Due to the stability of the EVs and the development of detection methods, HMGB1+ EVs can be a promising biomarker for sepsis diagnosis." (PMID 34743181, 2021). "Accumulating evidence suggests that HMGB1-RAGE binding is associated with a diverse array of inflammatory disorders, including sepsis, atherosclerosis, rheumatoid arthritis, neurological diseases and diabetic nephropathy." (PMID 33925132, 2021).